PDHA1 (pyruvate dehydrogenase E1 subunit alpha 1)
Diseases named in the same sentence as PDHA1 in open-access papers (continued):
Sharing a sentence is not in itself a finding about the gene and the disease.
gastric cancer (16 papers, 2021 to 2025). A primary or metastatic malignant neoplasm involving the stomach. "MiR-21-5p was elevated in specimens of gastric cancer, while PDHA1 expression was inversely linked with it." (PMID 41476448, 2025). "Downregulation of PDHA1, a gate-keeper enzyme-linked between glycolysis and the mitochondrial citric acid cycle, has been associated with poor survival in gastric cancer and esophageal squamous cancer." (PMID 35923577, 2022). "In gastric cancer, a low level of PDHA1 was associated with a poor prognosis." (PMID 36312586, 2022). "Decreased levels of PDHA1 increased glycolysis, which promoted gastric cancer growth and metastasis." (PMID 41476448, 2025). "Suppression of PDHA1 expression leads to a reduction in pyruvate dehydrogenase complex activity, consequently facilitating tumor glycolysis and promoting gastric cancer growth." (PMID 38114959, 2023). "Aberrant expression of PDHA1 and PDHB, which were involved in glycolytic regulation, was also closely associated with poor prognosis in gastric cancer patients." (PMID 35790864, 2022). "In gastric cancer, the expression level of PDHA1 was significantly decreased in intestinal-type, diffuse-type, and mixed-type gastric cancer." (PMID 36117848, 2022). "In contrast, another study reported that low expression of PDHA1 predicted poor prognosis in gastric cancer." (PMID 35223866, 2021). "Researchers found a connection between PDHA1 downregulation and a bad prognosis for gastric cancer." (PMID 41476448, 2025). "We conducted molecular experiments to validate our findings, and the results of Western blot analysis revealed notable disparities in the expression levels of FDX1, LIAS, DLAT, DLST, GCSH, PDHB and PDHA1 in gastric cancer cells between the CSRS‐Low (AGS) and CSRS‐High (HGC‐27) subtypes." (PMID 38898987, 2024). "Furthermore, cuproptosis also has a crucial influence on tumors in other ways, such as increasing glycolysis by downregulating PDHA1 expression and thus promoting gastric cancer development." (PMID 37511958, 2023). "Another study showed that low expression of PDHA1 indicated poor prognosis in gastric cancer." (PMID 38012558, 2023). "Immunohistochemical results showed that the expression of PDHA1 protein in gastric cancer tissue was significantly lower than that in adjacent gastric mucosal tissue, and the expression of PDHA1 in poorly differentiated gastric cancer was lower than that in well-differentiated gastric cancer." (PMID 36117848, 2022). "Decreased PDHA1 protein expression was also found to predict poor prognosis in gastric cancer." (PMID 36298586, 2022). "Down-regulation of PDHA1 (pyruvate dehydrogenase E1 subunit alpha 1), an important enzyme complex in cancer metabolism, could promote glycolysis and accelerate the progression of gastric cancer cells." (PMID 33996533, 2021). "Finally, they suggested that miR-21-5p may target PDHA1 to control a metabolic shift and cancer progression in gastric cancer, suggesting a possible function for this pathway in the therapy of gastric cancer." (PMID 41476448, 2025). "Among them, DLD and PDHA1 were differentially expressed in colon cancer, and DLAT, DLD, and PDHA1 were differentially expressed in gastric cancer and liver cancer." (PMID 36960059, 2023).
lung carcinoma (13 papers, 2015 to 2025). "We found that a high PDHA1 expression level was associated with poor prognosis in patients with lung cancer and STAD." (PMID 36003495, 2022). "In the case of lung cancer, the patients harboring the higher p-PDHA1 and PKM2 levels revealed much poorer survivability." (PMID 35740278, 2022). "The effect of PDHA1 silencing on lung cancer cell growth/proliferation was also explored by performing doubling assays." (PMID 35083212, 2021). "In addition, the lung cancer patients with the higher p-PDHA1 and PKM2 levels, when determined by Western blotting of tumor samples, markedly reduced survival probability." (PMID 35740278, 2022). "In addition to CDKN2A, genes, including DLD, LIPT1, GLS, PDHB, and PDHA1, also have significant CNVs, indicating the heterogeneity of lung cancer tissue." (PMID 36712848, 2022). "Our results suggest that PDHA1 may affect the lung cancer cell proliferation, invasion, migration, and chemoresistance, thereby affecting lung cancer progression." (PMID 35083212, 2021). "Deletion of PDHA1 exon 8 in mouse embryonic fibroblasts only modestly reduced the proliferative rate in complete medium, while substantial reductions in PDHA1 expression in H460 lung cancer cells had even less impact on the doubling time unless lipids were removed from the medium." (PMID 26137220, 2015). "By systematically analyzing the genetic alterations of 10 cuproptosis-related genes in lung adenocarcinoma, we found that CDKN2A, DLAT, LIAS, PDHA1, FDX1, GLS, and MTF1 were differentially expressed between lung cancer tissues and adjacent tissues." (PMID 36712848, 2022). "Intriguingly, based on our single-cell RNA-seq data, we classified TME cells in lung cancer into seven main cell types and discovered that FDXL, DLD, SLC3A1, and PDHA1 were differentially expressed in macrophages." (PMID 36263125, 2022). "In a word, our study showed that FDX1, a key enzyme for cuproptosis, affected the prognosis of lung cancer patients by influencing the expression of GLS, PDHA1, PDHB, DLAT, and MTF1." (PMID 36620594, 2022). "FDX1 affects the prognosis of lung cancer by altering the expression of cuproptosis-related signature (GLS, PDHA1, PDHB, MTF1, and DLAT), which more strongly confirms that the prognosis of lung cancer patients is closely related to the occurrence of cuproptosis." (PMID 36620594, 2022). "Specifically, we hypothesized that PDH inhibition or PDHA1 knockdown might play a role in EMT and chemoresistance and investigated how disruption of PDH activity influenced the molecular events triggering these changes using lung cancer cells as a model." (PMID 35083212, 2021).
lactic acidosis (9 papers, 2009 to 2025). Metabolic acidosis characterized by the accumulation of lactate in the body. "Based on the findings of this review, dichloroacetate will have an effect on most PDHA1 pathogenic variant and can act as a temporary treatment to reduce the lactic acidosis, a common symptom of PDH deficiency." (PMID 35996497, 2022). "Meanwhile, cognitive impairment is reported to be caused by the accumulation of lactate which can lead to congenital lactic acidosis, a common symptom shown for patients carrying the pathogenic variant of PDHA1 gene." (PMID 35996497, 2022). "As the catalytic component of pyruvate dehydrogenase (PDH), pyruvate dehydrogenase E1 (PDHA1) is located in the X chromosome and loss-of-function PDHA1 mutation appear serious lactic acidosis." (PMID 36518756, 2022). "Germline mutations in human PDHA1 can cause neurological deficits, hypotonia, brain abnormalities, and lactic acidosis that is often fatal to infants." (PMID 34749809, 2021). "Only the heterozygous missense change NM_000284.3 (PDHA1): c.1100A>T (p.His367Leu) affected a gene known to cause lactic acidosis and/or Leigh syndrome, and was therefore considered the most plausible disease-causing variant." (PMID 31673819, 2019). "PDHA1 resides on the X chromosome in both humans and mice, and human males hemizygous for loss-of-function PDHA1 mutations display severe lactic acidosis." (PMID 26137220, 2015). "Previously, SC35 was reported to be responsible for aberrant splicing of the E1α Puryvate Dehydrogenase (PDHA1) mRNA in mental retardation with lactic acidosis." (PMID 19909517, 2009). "In humans, PDHA1 mutations constitute ∼80% of cases of Leigh disease displaying with severe early-onset neurodegenerative symptoms, PDC enzyme activity reduced to 30%, and lactic acidosis with ∼4-fold increase in pyruvate and lactate plasma levels." (PMID 40904733, 2025).
cholangiocarcinoma (8 papers, 2018 to 2023). A carcinoma that arises from the intrahepatic biliary tree (intrahepatic cholangiocarcinoma) or from the junction, or adjacent to the junction, of the right and left hepatic ducts (hilar cholangiocarcinoma). "In cholangiocarcinoma, elevated PGC1α increased PDHA1 and mitochondrial pyruvate carrier 1 expression through the transcription program, thereby promoting cancer metastasis." (PMID 37056926, 2023). "The upregulation of PDHA1 could promote the metastasis of cholangiocarcinoma." (PMID 35223866, 2021). "We further investigated the levels of p-PDHA1 and PKM2 in liver tissue from patients with human hepatocellular carcinoma (HCC), hepatoblastoma (HB), and cholangiocarcinoma (ChC)." (PMID 37761999, 2023). "SIRT3, downregulated in cholangiocarcinoma (CCA) patients, can prevent tumor progression by inhibiting the HIF1α/PDK1/PDHA1 pathway." (PMID 35136826, 2022).
hepatocellular carcinoma (8 papers, 2022 to 2025). A malignant tumor that arises from hepatocytes. "In hepatocellular carcinoma (HCC), PDHA1 expression has been found to be predominantly associated with immune cell infiltration and six immune checkpoint-related genes." (PMID 41050056, 2025). "On the other hand, OE of PDHA1 suppressed the glucose uptake and lactate production in hepatocellular carcinoma cells, indicating reduced aerobic glycolysis." (PMID 40090587, 2025). "Inhibition of PDHA1 increases glycolysis and glucose consumption, which promotes esophageal squamous cell carcinoma and hepatocellular carcinoma growth." (PMID 38671021, 2024). "In a recent study, it was reported that insulin induced the phosphorylation of PDHA1 at Ser293 in HepG2 hepatocellular carcinoma cells through the RhoA/ROCK/GSK-3β signalling pathway." (PMID 37761999, 2023). "Insulin stimulates the phosphorylation of PDHA1 at the Ser293 residue, leading to a reduced PDHA1 enzyme activity in HepG2 hepatocellular carcinoma cells." (PMID 37761999, 2023). "It has been reported that overexpression of PDHA1 can inhibit aerobic glycolysis and result in mitochondria-mediated apoptosis in hepatocellular cancer." (PMID 37056926, 2023). "Specifically, insulin enhances the phosphorylation of pyruvate dehydrogenase E1α (PDHA1) at the Ser293 residue and promotes the proliferation of HepG2 hepatocellular carcinoma cells." (PMID 37761999, 2023). "Recently, we reported that insulin induces an increase in p-Ser293 PDHA1 along with p-Ser473 Akt levels in HepG2 hepatocellular carcinoma cells." (PMID 35740278, 2022). "Insulin was reported to increase p-Ser293 PDHA1 (p-PDHA1) levels in HepG2 and Huh7 hepatocellular carcinoma cells." (PMID 35740278, 2022). "In contrast to normal hepatocytes, insulin enhanced p-PDHA1 level and induced proliferation of hepatocellular carcinoma HepG2 cells." (PMID 35740278, 2022). "Although insulin has been well established to regulate gene expression through other pathways such as the Ras signaling pathway, we proposed in this study a novel mechanism by which insulin regulates gene expression through p-PDHA1 along with PKM2 in hepatocellular carcinoma HepG2 cells." (PMID 35740278, 2022). "However, the role of p-PDHA1 in hepatocellular carcinoma HepG2 cells due to insulin is poorly understood." (PMID 35740278, 2022). "Indeed, insulin sensitively augmented both PDHA1 and p-PDHA1 levels in hepatocellular carcinoma cell lines." (PMID 35740278, 2022). "In the previous report, we reported that insulin increased p-ser293 PDHA1 and PKM2 levels in HepG2 and Huh7 hepatocellular carcinoma cells." (PMID 37761999, 2023).
Sepsis (8 papers, 2015 to 2025). Sepsis is defined as life-threatening organ dysfunction caused by a dysregulated host response to infection. "Acting as an upstream deacetylase, SIRT3 regulates the acetylation level of pyruvate dehydrogenase E1 component subunit alpha (PDHA1) in renal tubular cells, participating in the occurrence and development of sepsis-associated acute kidney injury (SAKI)." (PMID 39234245, 2024). "Existing studies have shown that GPX4 is a negative regulator of ferroptosis, and activation of PDHA1 can ameliorate sepsis-induced acute kidney injury." (PMID 41445732, 2025). "Gene expressions of enzymes of the pyruvate dehydrogenase complex (Pdha1, Pdhb) were unaffected or decreased throughout sepsis, whereas pyruvate dehydrogenase kinase 3 (Pdk3), but not 1 (Pdk1), was upregulated." (PMID 39821755, 2025). "In sepsis, pyruvate dehydrogenase alpha 1 (PDHA1) is predominantly upregulated in renal tubular epithelial cells, where its acetylation-mediated inactivation drives excessive lactate production." (PMID 40806283, 2025). "Downregulation of SIRT3 expression in renal tissues and HK-2 cells after sepsis results in an elevation of PDHA1 acetylation levels coupled with diminished PDHA1 activity." (PMID 39234245, 2024). "Since PDH activity is often inhibited in patients with sepsis, modification of PDHB and PDHA1 seems to significantly influence the development of sepsis." (PMID 39539553, 2024). "In sepsis-induced acute kidney injury (SAKI), down-regulation of SIRT3 mediates hyperacetylation and inactivation of pyruvate dehydrogenase E1 subunit alpha 1 (PDHA1), leading to excessive lactate production." (PMID 40153584, 2025).
melanoma (7 papers, 2021 to 2025). A malignant, usually aggressive tumor composed of atypical, neoplastic melanocytes. "Moreover, we detected that PD-L1 expression was positively correlated with some cuproptosis-related genes (CDKN2A, FDX1, LIPT1, and MTF1), but negatively correlated with other cuproptosis-related genes (ATP7B, DLST, and PDHA1) in an analysis of 470 melanoma patients." (PMID 35837286, 2022). "In particular, CPI613, a lipoic acid analog that inhibits PDHA1 and OGDH, has been shown to dramatically attenuate the progression of melanoma and improve the therapeutic efficacy of anti-PD-1 against this tumor." (PMID 40721981, 2025). "They discovered that 11 out of 12 genes were upregulated in melanoma tissues and that three genes (LIPT1, PDHA1, and SLC31A1) have predictive value for the prognosis." (PMID 36454396, 2022). "The combination of correlation analysis and prognosis analysis indicated that the expression of most cuproptosis-related genes was positively correlated with each other, and three genes (LIPT1, PDHA1, and SLC31A1) had a prognostic value in melanoma." (PMID 35837286, 2022). "However, the expression of PDHA1, PDHB, and GLS was significantly higher in melanoma than in normal tissues." (PMID 36824136, 2023). "Similarly, other enzymes regulating the TCA cycle, such as pyruvate dehydrogenase subunit 1 (PDHA1) and oxoglutarate dehydrogenase (OGDH), are found to be hyperactivated in melanoma, highlighting the importance of citrate metabolism in shaping the tumor metabolic landscape." (PMID 40721981, 2025). "CRGs with low and moderate CNV, such as PDHA1, DLAT, GLS, and LIAS, were overexpressed in CRC comparison to those in normal melanoma samples, whereas CRGs with high CNV, such as PDHB, were significantly increased in melanoma samples, implying that CNV may regulate CRG mRNA expression." (PMID 36824136, 2023).
ovarian carcinoma (7 papers, 2017 to 2025). A malignant neoplasm originating from the surface ovarian epithelium. "In ovarian cancer, low PDHA1 expression is associated with higher pathological stage and lower overall survival." (PMID 36117848, 2022). "Several studies have found that the expression level of the PDHA1 gene is elevated in various cancers such as ovarian cancer, and high expression levels are closely related to the malignancy and prognosis of tumors." (PMID 37006250, 2023). "Several studies have examined the relationship between PDHA1 expression and the prognosis and survival of ovarian cancer patients." (PMID 28617852, 2017). "Recently, we demonstrated that the inhibition of the TCA cycle utilizing the inhibitor CP1–613, which targets TCA cycle enzymes pyruvate dehydrogenase (PDHA1) and 2-oxoglutarate dehydrogenase (OGDH), significantly decreased the growth of xenografts derived from resistant ovarian cancer cells." (PMID 40386427, 2025).
esophageal cancer (6 papers, 2021 to 2025). A primary or metastatic malignant neoplasm involving the esophagus. "In terms of its effect on cancer progression and development, decreased expression of PDHA1 was verified to be associated with an unfavorable outcome in a variety of types of cancers including ovarian, liver and esophageal cancer." (PMID 36518756, 2022). "Patients with esophageal cancer were categorized into two groups, namely high expression and low expression, based on their PDHA1 expression." (PMID 38159255, 2023). "Previous reports with PDHA1 KO esophageal cancer model showed enhanced glycolytic rate corroborating our hypothesis of PDHA1 S152A mutants with higher enzymatic activity." (PMID 40090587, 2025). "Moreover, PDHA1 knockout significantly accelerated glycolysis, increased the consumption of glucose and glutamine, and suppressed oxidative phosphorylation, thereby causing the Warburg effect, in the KYSE450 esophageal cancer cell line." (PMID 33996533, 2021).
Leigh syndrome (6 papers, 2009 to 2025). "PDHA1 deficiency has been found in a variety of neurodegenerative diseases, such as AD, epilepsy, and Leigh’s syndrome." (PMID 34720870, 2021). "One month later, we found that the child had a de novo mutation (NM_000284.4: c.1167_1170del) in the PDHA1 gene through clinical exome sequencing, and corrected his diagnosis from Guillain‐Barré syndrome to Leigh syndrome." (PMID 33661577, 2021). "The observed mutation in PDHA1 has been described in patients with Leigh syndrome, a condition characterized by extensive genetic heterogeneity, since it can be due to mutations in several genes (OMIM 256000) and is thus a paradigm for the utility of the proposed assay." (PMID 19852779, 2009). "Pyruvate dehydrogenase E1 component subunit alpha (PDHA1) is an essential component in the process of glucose metabolism, and its deficiency exists in various diseases such as Alzheimer’s disease (AD), epilepsy, Leigh’s syndrome, and diabetes-associated cognitive decline." (PMID 34720870, 2021).
liver cancer (6 papers, 2017 to 2023). An epithelial or non-epithelial malignant neoplasm that arises from the liver. "Then, we assessed the survival probability of liver cancer patients with high versus low expressing p-PDHA1." (PMID 35740278, 2022). "In keeping with our result, Lyudmyla G and his group found that enforced overexpression of PDHA1 gene caused metabolic reprograming towards mitochondrial OXPHOS and apoptosis in human liver cancer cells." (PMID 28076853, 2017). "We then analyzed p-PDHA1 levels by using Western blotting from human liver cancer patients." (PMID 35740278, 2022). "Of interest, we observed that p-PDHA1 and PKM2 were localized in the nucleus in liver cancer patients." (PMID 37761999, 2023). "Overexpression of PDHA1 in liver cancer cells can reduce the activity of PDH and affect the metabolic state of liver cancer cells, thereby inhibiting the proliferation of liver cancer cells and promoting the apoptosis of liver cancer cells." (PMID 36117848, 2022). "Contrary to our expectation, p-PDHA1 did not display differential survival for the liver cancer patients analyzed, likely due to alteration of endogenous insulin concentration in patients." (PMID 35740278, 2022). "The localization of p-PDHA1 and PKM2 in HCC, HB, and ChC tissues were significantly higher in the nucleus compared to the control non-neoplastic hepatocyte tissues around tumour tissues, suggesting that nuclear localization of p-PDHA1 and PKM2 may be a characteristic feature of liver cancer tissue." (PMID 37761999, 2023).